IL16 (interleukin 16)
Diseases named in the same sentence as IL16 in open-access papers (continued):
Sharing a sentence is not in itself a finding about the gene and the disease.
pneumonia (4 papers, 2021 to 2025). An acute, acute and chronic, or chronic inflammation focally or diffusely affecting the lung parenchyma, caused by an infection in one or both of the lungs (by bacteria, viruses, fungi, or mycoplasma.). "Relative to controls, cytokines that were significantly elevated in the pneumonia cohort at 24 and/or 48 h after inoculation (evolution phase) were IL‐1β, IL‐6, IL‐15, IL‐16, IL‐17a, IP‐10, MCP‐1, MIP‐1β, and TARC; IL‐5 was significantly elevated at 168 h (resolution phase)." (PMID 40947770, 2025). "High serum IP-10 and M-CSF levels accompanied by low IL-16, TNF-β, and PDGF-BB levels may be associated with the development of pneumonia." (PMID 38133713, 2024). "However, the levels of CTACK, Eotaxin, IL-16, macrophage migration inhibitory factor (MIF), and MCP-1 in the pneumonia group were significantly lower than those in the bronchitis group." (PMID 36119044, 2022).
renal cell carcinoma (4 papers, 2013 to 2022). "And the contribution of IL-16 rs4778889 has been demonstrated in correlation to renal cell cancer in a Chinese population." (PMID 30671474, 2018).
schizophrenia (4 papers, 2023 to 2024). A major psychotic disorder characterized by abnormalities in the perception or expression of reality. "The current study also show that plasma IL-16 levels are an independent factor in associating with the onset of schizophrenia in both first-episode and relapsing patients." (PMID 37270510, 2023). "There are few studies on the association between schizophrenia and IL-16." (PMID 37270510, 2023). "In the models, serum IL-16 levels were found to be an independent factor, which can associate with the onset of schizophrenia in both the first-episode group and control group (OR = 1.034, P = 0.002) and recurrence group and control group (OR = 1.049, P = 0.003)." (PMID 37270510, 2023). "Consistently, several studies found that the IL-15, IL-16, and IL-8 levels in patients with schizophrenia are associated with a poor response to antipsychotic treatment, and increased IL-8 levels are significantly associated with more severe psychiatric symptoms in patients." (PMID 37270510, 2023). "The IL-16 level may be an independent factor associating with the onset of schizophrenia." (PMID 37270510, 2023). "Serum IL-1β levels in first-episode schizophrenia and serum IL-16 levels in relapsing schizophrenia were correlated with the parts of psychiatric symptoms." (PMID 37270510, 2023). "In the study, IL-16 levels were an independent variable of the onset of schizophrenia both in the first-episode (OR = 1.034, P = 0.002) and recurrence groups (OR = 1.049, P = 0.003)." (PMID 37270510, 2023). "In conclusion, the levels of IL-1β and IL-16 are different between patients with schizophrenia and healthy subjects." (PMID 37270510, 2023). "ROC curve were used to evaluate the significance of IL-16 level in the diagnosis and prediction of schizophrenia." (PMID 37270510, 2023). "Plasma IL-1β of first-episode schizophrenia and plasma IL-16 of relapsing schizophrenia were correlated with the parts of psychiatric symptoms." (PMID 37270510, 2023). "The binary logistic regression analysis was used to explore whether serum IL-1β and IL-16 levels could relate to the onset of schizophrenia." (PMID 37270510, 2023). "Serum IL-1β and IL-16 levels were different between patients with schizophrenia and healthy people." (PMID 37270510, 2023). "Additionally, interleukin 16 protein levels have been reported to be altered in a molecular profiling study on serum samples of MDD patients and to be associated with symptom severity in schizophrenia." (PMID 39367879, 2024). "The current study indicated that the plasma level of IL-16 in patients with first-episode and relapsing schizophrenia was significantly higher than in healthy people, suggesting that IL-16 may play an important role in the occurrence and development of schizophrenia." (PMID 37270510, 2023). "IL-16 levels may be an independent factor for the onset of schizophrenia." (PMID 37270510, 2023). "At present, there is a lack of research on the relationship between IL-16 and schizophrenia, but research on IL-16 and mental illness existed." (PMID 37270510, 2023). "However, research on the relationship between IL-16 and schizophrenia is lacking, which needs to be paid more attention in the future." (PMID 37270510, 2023).
antineutrophil cytoplasmic antibody-associated vasculitis (3 papers, 2020 to 2025). "In antineutrophil cytoplasmic antibody-associated vasculitis, IL-16 was correlated with the vasculitis damage index and was presumed to be involved in vascular fibrosis." (PMID 35172901, 2022). "We investigated whether IL-16 plays a pro- or an anti-inflammatory role in antineutrophil cytoplasmic antibody-associated vasculitis (AAV)." (PMID 32264927, 2020).
Arthritis (3 papers, 2021 to 2026). Inflammation of a joint. "Our group has previously reported observation that SLE patients with active nephritis or arthritis had high levels of circulating IL-16, while patients with CLE had lower." (PMID 33931094, 2021). "Walnut leaf ethanolic extract ameliorated acute inflammation and arthritis in rats by increasing the levels of blood IL‐4, besides attenuating TNF‐α, NF‐κB, IL‐6, IL‐16, COX‐2, and prostaglandin E2 (PGE2) amounts in blood, which resulted in reduced paw edema and arthritic development." (PMID 41179368, 2025).
Cerebral ischemia (3 papers, 2013 to 2020). Restriction of arterial blood supply to the brain associated with insufficient oxygenation to support the metabolic requirements of the tissue. "Interleukin-16 (IL-16) is identified as a proinflammatory cytokine that is a key element in the ischemic cascade after cerebral ischemia." (PMID 24288444, 2013). "IL16 exerts a chemoattractant, pro-inflammatory and apoptotic activity contributing to a further worsening of ischemic damage in experimental and human brain ischemia." (PMID 23874624, 2013).
cervical cancer (3 papers, 2014 to 2025). A primary or metastatic malignant neoplasm involving the cervix. "rs1131445 affects IL-16 expression by interfering with the suppressive function of miR135b and this variant is significantly associated with cervical cancer risk." (PMID 24465869, 2014). "We found that the SNP rs1131445 C allele in the 3′-UTR of IL-16 was associated with an increased risk of cervical cancer." (PMID 24465869, 2014). "Our findings of serum IL-16 elevation following cervical carcinogenesis and the notable association of IL-16 with cervical cancer risk suggest that IL-16 could regulate cervical carcinogenesis." (PMID 24465869, 2014). "In conclusion, our data suggested that rs1131445, as a functional variant, could modulate the individual risk of cervical cancer likely by deregulating the post-transcriptional regulation of miRNA-135b on IL-16 expression." (PMID 24465869, 2014). "Given the important regulatory roles of IL-16 release in the immune response and the consequent level of the local inflammatory microenvironment, individuals who carry the rs3134615 C allele would be expected to have elevated risk for cervical cancer." (PMID 24465869, 2014). "The serum IL-16 of patients with cervical cancer significantly increased compared to controls (P = 0.001)." (PMID 24465869, 2014). "We selected 100 patients with cervical cancer and 80 controls from the subjects of Study 2 and examined their serum IL-16 levels by ELISA." (PMID 24465869, 2014). "Additional functional analyses are also required to clarify the exact roles of IL-16 in cervical cancer genesis and progression in the future." (PMID 24465869, 2014). "An ELISA indicated that the serum IL-16 of patients with cervical cancer was elevated (vs. controls, P = 0.001) and correlated with the rs1131445 genotype." (PMID 24465869, 2014). "Here, we provide the first evidence that rs1131445 in the miR-135b binding site of IL-16 3′-UTR, which can affect IL-16 protein expression by interfering with miR135b suppressive function, was significantly associated with the risk of cervical cancer." (PMID 24465869, 2014). "The roles of IL-16 in cervical cancer pathophysiology remain largely unclear." (PMID 24465869, 2014). "Moreover, in patients with cervical cancer, there was a marked correlation between the serum IL-16 and rs1131445 genotype (P = 0.001)." (PMID 24465869, 2014). "Given the observed notable association between the rs1131445 and cervical cancer risk, we further investigate the serum IL-16 levels in controls and patients with cervical cancer as well as the potential regulatory effects of the rs1131445 genotype on serum IL-16." (PMID 24465869, 2014). "The upregulation of miR-135b has been found in cervical cancer, which could inhibit the expression of IL-16 by targeting its 3′-UTR." (PMID 24465869, 2014). "Furthermore, we did not note any statistically significant association of serum IL-16 with the clinical stage and histological type of the cervical cancer (data not shown)." (PMID 24465869, 2014).
dementia (3 papers, 2021 to 2024). Loss of intellectual abilities interfering with an individual's social and occupational functions. "Elevated IL-16 levels have been linked to increased risk of white matter lesions in patients with mild cognitive impairment, and we speculate that they may be associated with decrease white matter and heightened dementia risk in patients with iNPH." (PMID 38974901, 2024).
Insulin resistance (3 papers, 2022 to 2025). Increased resistance towards insulin, that is, diminished effectiveness of insulin in reducing blood glucose levels. "Patients with severe CAP have inflammatory immune activation (manifested by an increased IL-6 level and IL-16/IL-10 ratio), acquired growth hormone (GH) resistance, and insulin resistance." (PMID 35619955, 2022).
lung carcinoma (3 papers, 2016 to 2024). "Compared with the genotype “A/A-G/A”, IL-16 rs859 “G/G” showed a decrease in lung cancer susceptibility with OR of 0.65 (95% CI = 0.44-0.96, P = 0.029) in recessive model after adjusting for age, gender, smoking status, and alcohol drinking status." (PMID 30671474, 2018). "In this study, the polymorphisms in 3′UTR of IL-16 have been demonstrated in correlation to lung cancer for the first time." (PMID 30671474, 2018). "And significant associated evidences have been detected between IL-16 rs859 and lung cancer susceptibility." (PMID 30671474, 2018). "Our results yield a new insight on IL-16 SNPs in mRNA untranslated region and provide possible candidate for lung cancer risk assessment in Chinese Han population." (PMID 30671474, 2018). "In this study, the polymorphism rs859 in 3′UTR of IL-16 has been demonstrated in correlation to lung cancer for the first time." (PMID 30671474, 2018). "As the results, significant relationships were found between IL-16 rs859 and lung cancer susceptibility in recessive model (OR= 0.65, 95% CI: 0.44-0.96, P= 0.029) and log-additive model (OR= 0.76, 95% CI: 0.60-0.96, P= 0.019)." (PMID 30671474, 2018). "Additionally, various well-discussed functions of untranslated region also suggest the other putative effects of IL-16 rs859 in miRNA stability, protein translation, and localization, which might be implicated in lung cancer development as well." (PMID 30671474, 2018). "As a main result of our research, IL-16 3′UTR variant rs859, was associated with lung cancer risk in Chinese Han population." (PMID 30671474, 2018). "Our results suggested a significant relationship between IL-16 3′UTR rs859 and lung cancer risk in a Chinese Han population." (PMID 30671474, 2018). "In this study, polymorphisms in 3′-untranslated region of IL-16, CYP24A1, and FBN1 were determined in 322 lung cancer patients and 384 healthy controls with the usage of Sequenom MassARRAY." (PMID 30671474, 2018). "Likewise, IL-16 rs859 exerted a protective role in lung cancer development among males (recessive model: ref: A/A-G/A, adjusted OR = 0.62, 95% CI = 0.39-0.99, P = 0.045; log-additive model: adjusted OR = 0.73, 95% CI = 0.55-0.97, P =0.029)." (PMID 30671474, 2018). "Our research demonstrated that genetic variant rs859 of IL-16 3′UTR was associated with lung cancer risk in Chinese Han population and the result might be exploited as a new biomarker for lung cancer assessment and prevention." (PMID 30671474, 2018). "When stratified by drinking status, IL-16 rs859 was found to modulate the susceptibility to lung cancer among individuals without drinking history (log-additive model: adjusted OR = 0.74, 95% CI = 0.55-0.98, P = 0.036)." (PMID 30671474, 2018). "Since IL-16 has been proved associated with cancer progression and susceptibility, the abnormal expression of IL-16 because of 3′UTR alterations might result in the disordered modulation implicated in the generation and development of lung cancer." (PMID 30671474, 2018). "While CD4 is the primary receptor for IL-16, certain cells can respond to IL-16 through alternative receptors like CD9, for example, mastocytes or lung cancer cells, as well as via CD4- and CD9-independent mechanisms." (PMID 39408600, 2024). "For instance, the SAA1 lung cancer biomarker, neuro-inflammation factor MMP1, the chemokine ligands (C-C motifs) CCL2, CCL5, and CCL20, and cytokines such as IL6, IL8, IL16, were all significantly modulated." (PMID 26950733, 2016).
mild cognitive impairment (3 papers, 2022 to 2025). "Two studies reported significantly different concentrations of markers in individuals with MCI: CXCL11, CCL13, and CCL15 were increased, and CXCL16 and IL-16 were decreased in individuals with mild cognitive impairment compared to controls." (PMID 40711681, 2025).
nasopharyngeal carcinoma (3 papers, 2013 to 2024). A carcinoma arising from the nasopharyngeal epithelium. "Our previous study has shown that the IL-16 rs11556218 T/G polymorphism was significantly associated with susceptibility to both hepatocellular and nasopharyngeal carcinoma." (PMID 25954818, 2015).
perinatal asphyxia (3 papers, 2019 to 2025). A disorder caused by a lack of blood flow or gas exchange to or from the fetus in the period immediately before, during, or after the birth process. "Elevated cord blood IL-16 levels have also been linked to severely abnormal neurodevelopmental outcomes at three years of age in infants with perinatal asphyxia and hypoxic-ischemic encephalopathy." (PMID 40948499, 2025). "Cohort Study of Ahearne and co-worker is the firstreport that measured the association of IL-16 in neonates with perinatal asphyxia atbirth and long-term outcome." (PMID 31435616, 2019).
thrombosis (3 papers, 2017 to 2021). "Neutralizing antibodies against SARS-CoV-2 can activate IL-18 and IL-16, myeloid chemotaxis, and activation of lymphocytes, monocytes, and natural killers, which lead to neutrophil activation, hypercoagulation, and thrombosis." (PMID 34858909, 2021). "In an attempt to increase the discrimination ability of the model, rs11556218 in IL16 and rs34708521 in SPEF2 that were initially investigated for their association with thrombosis but later found to be also associated with pancreatitis, were added to the analysis." (PMID 28574850, 2017). "Furthermore, rs11556218 in IL16 and rs34708521 in SPEF2 were both associated with thrombosis (p=0.01 and p=0.03, respectively) and pancreatitis (p=0.02)." (PMID 28574850, 2017). "Interestingly, rs3809849 in the MYBBP1A gene was associated with allergy, pancreatitis, thrombosis, event-free survival (EFS) and overall survival, while rs11556218 in IL16 gene and rs34708521 in SPEF2 gene were both associated with thrombosis and pancreatitis." (PMID 35582721, 2019).
type 1 diabetes (3 papers, 2011 to 2021). "A previous animal study found that neutralizing anti-IL16 mAb can prevent insulitis and type 1 diabetes in mice." (PMID 28425483, 2017). "The SNP rs12416605, located in human type 1 diabetes IDDM10 locus, changes the seeding sequence (UGU[G/A]CCC) of miRNA miR-938 and potentially alters miR-938 targets, including IL-16 and IL-17A." (PMID 22014115, 2011).
acute myocardial infarction (2 papers, 2019 to 2025). Necrosis of the myocardium, as a result of interruption of the blood supply to the area. "IL-16 might play an important role in the inflammatory process of patients suffering from acute myocardial infarction and correlates with inflammatory cell activation." (PMID 31547124, 2019).
cerebral infarction (2 papers, 2013 to 2024). An ischemic condition of the brain, producing a persistent focal neurological deficit in the area of distribution of the cerebral arteries. "In humans, early accumulation of IL16 after cerebral infarction has a role in the post-acute inflammatory response." (PMID 23874624, 2013). "Although the exact role of IL-16 in ICH is not defined, in patients with focal cerebral infarctions, IL-16 accumulates in the perivascular region to promote inflammation." (PMID 38114796, 2024).
Cirrhosis (2 papers, 2015 to 2022). A chronic disorder of the liver in which liver tissue becomes scarred and is partially replaced by regenerative nodules and fibrotic tissue resulting in loss of liver function. "In the healthy state, the communication probability exhibited by the MIF signaling pathway was insignificant, similar to that of IL16 in the cirrhosis state." (PMID 36221095, 2022). "From cirrhosis to cancer, macrophages and naïve CD4 + T cells employ autocrine and paracrine mechanisms to communicate in the IL16 signaling pathway." (PMID 36221095, 2022). "The ligand-receptor pair of IL16 and CD4 is activated in the interaction of macrophages and naïve CD4 + T cells, and in conversion from cirrhosis to the cancer." (PMID 36221095, 2022).
co-infection (2 papers, 2021 to 2023). "The expression of IL-16 in murine serum was increased significantly in the co-infection group than in the individual infection group by the ELISA test results." (PMID 35224069, 2021). "and C. perfringens co-infection was highly correlated with IFN-α, IFN-γ, IL-4, IL-13, IL-16, LITAF, TGF-β4 and TNFSF15 in the jejunum, indicating that Th2 type cytokines mainly participated in avian NE." (PMID 37240767, 2023).
colon cancer (2 papers, 2018 to 2023). "IL-16 plays a role in promoting cellular inflammation; BCl-6 plays a role in inhibiting apoptosis in colon cancer cells; and NFKBIZ plays a role in promoting the expression of the IL-17 inflammatory signaling pathway." (PMID 36839472, 2023). "The current study didn’t observe evidence of interaction between variant alleles of SNPs in previously reported genes- ALOX15, IL16, MDR1, NFkB, PTGS1 and PTGS2- with aspirin only use and CRC or colon cancer risk." (PMID 29425227, 2018).
dermatomyositis (2 papers, 2021). Dermatomyositis (DM) is a type of idiopathic inflammatory myopathy characterized by evocative skin lesions and symmetrical proximal muscle weakness. "Also, in another unbiased analysis of cutaneous proteome of CLE lesions, IL-16 was identified as the only cytokine differentially upregulated in CLE in comparison to dermatomyositis (DM)." (PMID 34768756, 2021).
emphysema (2 papers, 2012 to 2017). "In addition, integration of transcriptomics and protein expression profiles of PBMCs obtained from a large study cohort suggested an association between decreased IL-16 and emphysema; it also identified IL-16 cis-eQTL as a novel disease biomarker." (PMID 29376056, 2017).
fibrosis (2 papers, 2013 to 2014). the formation of excess fibrous connective tissue in an organ or tissue in a reparative or reactive process. "It has been shown that IL-16 expression is elevated in both murine and human fibrosis, therefore, IL-16 is a candidate biomarker for IPF." (PMID 25551570, 2014). "The LV IL-16 mRNA level was positively correlated with both the extent of LV fibrosis and EH in the TG mice." (PMID 23894370, 2013). "In summary, our present work provides the first evidence that IL-16 mediates cardiac inflammation leading to increased cardiac fibrosis and LV stiffness in HFpEF." (PMID 23894370, 2013).